RNU6-1156P (RNA, U6 small nuclear 1156, pseudogene)
Gene: Small nuclear RNA gene on chromosome 11 (125,574,719 to 125,574,818, forward strand). Ensembl gene ENSG00000222297.
Homologues: Orthologues: chimpanzee U6 (100% identical), macaque U6 (96% identical), dog U6 (74% identical), pig U6 (69% identical). Paralogues in human: RNU6-28P (90% identical), RNU6-86P (90% identical), RNU6-774P (89% identical), RNU6-1011P (88% identical), RNU6-11P (88% identical), RNU6-37P (88% identical), RNU6-12P (87% identical), RNU6-13P (87% identical), RNU6-242P (87% identical), RNU6-32P (87% identical), RNU6-338P (87% identical), RNU6-38P (87% identical), and 1286 more.